BRCA2 (BRCA2 DNA repair associated)
Diseases named in the same sentence as BRCA2 in open-access papers (continued):
Sharing a sentence is not in itself a finding about the gene and the disease.
breast tumors (continued). "Likewise, genomic regions harboring RARSL (6q15) and FAM26F (6q22.1) have been frequently deleted in BRCA2 associated breast tumors." (PMID 20174566, 2010). "Additionally, breast tumors occurring in individuals with germline BRCA1 or BRCA2 mutations typically fall into distinct subtypes." (PMID 20576095, 2010). "Analysis of the recurrent regions of chromosomal instability in BRCA1 or BRCA2 mutated breast tumors may point to loci and/or genes involved in development and progression of BRCA-associated hereditary breast cancer." (PMID 20735817, 2010). "The AURKA gain has been previously associated with BRCA2-mutated breast tumor development but our findings suggest that the functional interaction between AURKA and BRCA2 may be evolutionarily conserved." (PMID 20735817, 2010). "However the late age at which these breast tumors developed argues against their being caused by mutations in the BRCA1 or BRCA2 genes." (PMID 18307792, 2008). "Thus, it may suggest that among BRCA2-associated male breast tumors classified as HER2-negative, there may be a relevant proportion of HER2-low." (PMID 38339299, 2024). "Importantly, we found that these sites are susceptible to chromosome rearrangements in BRCA2-mutated breast tumors, suggesting that genomic instability in tumors with compromised BRCA2 function is due in part to pathologies linking transcription with replication and mitotic DNA repair." (PMID 36002001, 2022). "Nevertheless, the association of p16/pRb dysfunction to the basal/TNP subtype, identified here in BRCA2 mutated breast tumors, is similar to that reported in sporadic tumors suggesting that the events leading to the basal/TNP phenotype in carriers and noncarriers could be the same." (PMID 21958427, 2011). "In addition, BRCA2 germline variation concomitant with the presence of methylation in the promoter region was novel and interesting and emerged as a strong candidate for susceptibility to sporadic breast tumors." (PMID 21092294, 2010). "CD109, AHNAK2, and MFGE8 in breast BRCA1-mut cancers, and B3GNT7, CTSV, and GSDMC in BRCA2-mut breast tumors." (PMID 40647506, 2025). "This study reveals distinct patterns in the molecular profiles of breast tumors linked to mutations in BRCA1, BRCA2 and ATM." (PMID 40259910, 2025). "Similar to BRCA1 or BRCA2 deletion, copy number loss of each gene in the CK2–HTATSF1–TOPBP1 axis predicted higher HRD scores in TCGA breast tumors." (PMID 38762174, 2024). "In particular, high histologic grade breast tumors are more frequent among male BRCA2 PV carriers diagnosed at younger ages (<50 years) than among those diagnosed at older ages." (PMID 38339330, 2024). "As observed in ovarian and breast tumours, targeting poly (ADP-ribose) polymerase 1 (PARP1) in tumours with BRCA1 and breast cancer gene 2 (BRCA2) inactivation selectively causes cancer cell death, showing promise in clinical settings." (PMID 39271762, 2024). "This restoration resulted in a functional BRCA2 protein, effectively elucidating the clinical resistance observed in the new breast tumor in this case." (PMID 37743480, 2023). "In this regard, the work was aimed to evaluate CNA and mutations of the BRCA1, BRCA2, and PALB2 genes in the breast tumor of patients and their predictive and prognostic potential." (PMID 37628606, 2023). "A homologous recombination deficiency typically associates with “BRCAness” of breast tumors due to mutational inactivation of the BRCA1 and BRCA2 tumor suppressor genes, making these tumors susceptible to poly-ADP ribose polymerase (PARP) inhibitors." (PMID 37906280, 2023). "Breast tumors carrying BRCA1 mutants are linked to basal-like and triple-negative phenotypes, but those with BRCA2 mutations are generally of the luminal subtype." (PMID 35224098, 2022). "Breast tumors expressing BRCA2-001/Short were evenly split between patients that eventually recurred (54%) and those that did not (46%)." (PMID 36344544, 2022).
breast tumors (continued). "In agreement with the TCGA data, the degree of bi-allelic LoF was high; 96% for BRCA1 (both germline and somatic), 89 and 90% for BRCA2 (germline and somatic, respectively) in ovarian tumours and 86–91% and 75–86%, respectively, in breast tumours." (PMID 34979999, 2022). "Across all tumor samples, expression of BRCA2-001/Short was slightly more common in breast tumors (10/20; 50%) than in ovarian tumors (14/34; 42%)." (PMID 36344544, 2022). "In this study, we investigate transcriptomic data across multiple breast tumour datasets using differential variability analysis to identify genes that are associated with BRCA1 and BRCA2 pathogenic variant status and with different tumour subtypes." (PMID 34287743, 2021). "For instance, an individual is at a higher risk of getting “breast tumor,” “ovarian tumor,” and “prostate tumor,” when inheriting the supposed “breast tumor genes,” certain mutations in BRCA1 and BRCA2." (PMID 33833800, 2021). "BRCA2-T207A also affects chromosome alignment and segregation, leading to aneuploidy, a feature observed in BRCA2 breast tumors, a compound phenotype that underscores the possible clinical relevance of this variant." (PMID 34359619, 2021). "We also observed that most BRCA2 breast tumors had expression patterns similar to BRCAX, especially in the upregulated miRNAs cluster, whereas most BRCAX breast tumors exhibited a specific expression pattern in the downregulated miRNAs cluster." (PMID 32087690, 2020). "To define characteristic features of HRD tumors and analyze the correlations between BRCA1/BRCA2 and BC subtypes, we analyzed 981 breast tumors from the TCGA database using the signature analyzer." (PMID 32719318, 2020). "When heterozygously inactivated, it robustly facilitates breast tumor formation in Brca2 conditional knockout mice." (PMID 32980867, 2020). "Breast tumor DNA was subsequently extracted from a paraffin-embedded tissue block, containing approximately 40% of tumor cells, and BRCA2 c.9294C>G was detected in 57% of reads." (PMID 32468491, 2020). "We analyzed genomic data from breast tumors, with a focus on comparing tumors with BRCA1/BRCA2 gene mutations with common classes of sporadic breast tumors." (PMID 31182087, 2019). "The main goal of this study was to identify the principal characteristics that differentiate a family with BRCA1/BRCA2 pathogenic mutations from those with a VUS alteration and even from those BRCA1/BRCA2 WT and with sporadic breast tumors." (PMID 31244284, 2019). "According to a recently published study, only 9% of BRCA1-related breast tumours and 13% of BRCA2-related breast tumours were HER2 positive." (PMID 29928469, 2018). "Contralateral breast tumours occurred in 151 (6%) patients: in 37 (18%) of 201 BRCA1 mutation carriers, 17 (12%) of 137 BRCA2 mutation carriers, and 97 (4%) of 2395 BRCA-negative patients." (PMID 29337092, 2018). "Resveratrol, which binds and activates estrogen receptors, are important factor in the regulation of transcription of estrogen-responsive target genes and increases expression of BRCA1 and BRCA2 mRNA in breast tumor cell lines." (PMID 28674526, 2017). "Familial BRCA1 or BRCA2 mutant breast tumors tend to have a TNBC phenotype and often exhibit extreme levels of genomic instability." (PMID 27959926, 2016). "The purpose of this multicenter study was to evaluate Multiplicom's BRCA MASTR Dx kit to detect clinically important variants in BRCA1 and BRCA2 in FFT derived ovarian and breast tumor samples." (PMID 27793035, 2016). "For example, breast tumors and ovary tumors have common risk factors including hormone therapy, obesity, and inherited genetic risk such as BRCA1 and BRCA2." (PMID 26273658, 2015). "We identified 114 breast tumors, of which 71 (62.3 %) were BRCA1-associated and 43 (37.7 %) were BRCA2-associated." (PMID 26496879, 2015).
breast tumors (continued). "• apply the model on two case studies - normal vs PDAC tumour and BRCA1 vs BRCA2 familial breast tumour conditions - to decipher their roles in these tumours." (PMID 25521701, 2014). "Gene expression data: We have performed one of the largest gene expression profiling analyses of familial breast tumours (n = 74) and stratified them based on BRCA mutation status as BRCA1-, BRCA2- and non- BRCA1/2 tumours." (PMID 25521701, 2014). "We found that breast tumors from BRCA1 and BRCA2 mutation carriers display characteristic RNA expression patterns, allowing them to be distinguished from sporadic tumors." (PMID 23704984, 2013). "In the present study, frozen, primary breast tumors were collected from BRCA1 (n = 33) and BRCA2 (n = 22) mutation carriers and from sporadic cases (n = 128)." (PMID 23704984, 2013). "More studies are guaranteed to determine the role of miRNA more related to familial breast tumors and those specifically associated to the BRCA1 and BRCA2 mutated tumors." (PMID 22701724, 2012). "To gain insight into the biology of BRCA2-mutant breast tumors, we performed a supervised analysis looking for genes differentially expressed in BRCA2-mutant and control tumors." (PMID 23284877, 2012). "Breast tumors arising in BRCA1 mutation carriers are typically ER-negative, whereas most tumors in BRCA2 mutation carriers and sporadic cases are ER-positive." (PMID 22110403, 2011). "In this relation, it has been shown that chromosomal instability arises after inactivation of murine Brca2 gene, which is in agreement with complex chromosomal changes observed in human breast tumors derived from BRCA2 carriers." (PMID 21958427, 2011). "Previous studies have reported the methylation of BRCA2 in breast tumor but to the best of our knowledge, our study is the first to find methylated BRCA2 in benign breast disease." (PMID 22011321, 2011). "We detected low levels (nearly 10%) of the alternative transcript that lacks exon 3 BRCA2, using 185 sporadic breast tumours samples and some head and neck tumours and normal tissues samples." (PMID 21939546, 2011). "Distinctive patterns of global gene expression have also been shown between breast tumors with BRCA1 mutations and breast tumors with BRCA2 mutations." (PMID 20174566, 2010). "We also observe BRCA2 to play a major role at both genetic and epigenetic level in sporadic breast tumor pathogenesis." (PMID 21092294, 2010). "BRCA1 and BRCA2 positive nuclear staining was observed in 6 (30%) and 9 (45%) out of 20 breast tumors, respectively." (PMID 20230646, 2010). "The purpose of this study was to examine the potential involvement of the BRCA1 and BRCA2 genes in sporadic breast tumour development." (PMID 19589159, 2009). "Further research will be needed to examine the potential of the data presented here to predict BRCA1 or BRCA2 abnormalities in an independent population of breast tumours or cell lines." (PMID 19589159, 2009). "Our results confirm that AI at the BRCA1 and BRCA2 loci are common events in sporadic breast tumours, present in 37.4% (49/131) and 31.1% (42/135) of primary sporadic breast tumours, respectively." (PMID 16846527, 2006). "Genes whose products are known to interact with BRCA1 and/or BRCA2, or are down-regulated in breast tumours, are particularly attractive candidates, and can be prioritised for investigation." (PMID 16280053, 2005). "Histopathological features of BRCA1 and BRCA2 tumours have previously been characterised and compared with unselected breast tumours; however, familial non-BRCA1/2 tumours are less well known." (PMID 15642173, 2005). "Breast tumors were diagnosed in first- or second-degree female or male relatives of glioma patients with BRCA2 GVs in 3/5 families, strongly suggesting that the breast tumor patients also carry the BRCA2 GV and that it is the tumor-predisposing variant in these families." (PMID 41546701, 2026).
breast tumors (continued). "Moreover, patients with BRCA1/2- or PALB2 (partner and localizer of BRCA2)-mutant breast tumors that display heightened FLT1 expression in their tumor cells at pre-treatment are at high risk for progression on PARPi." (PMID 38956205, 2024). "However, breast tumors in BRCA1 and BRCA2 mutation carriers generally show different histopathology." (PMID 38059556, 2024). "NGS sequencing of the paraffin-embedded breast tumor block did not identify additional BRCA2 mutation as a second hit." (PMID 36833429, 2023). "In parallel to the cell viability results in murine 4T1 cell line, treatment with gene therapeutics (BRCA1 + NP and BRCA2 + NP) in syngeneic mouse model carrying 4T1-induced breast tumors, showed significant tumor regression pattern in comparison to the NP control group." (PMID 36631481, 2023). "Thus, the aim of the work was to evaluate the predictive and prognostic potential of DNA copy number aberrations and mutations in the BRCA1, BRCA2, and PALB2 genes in breast tumors." (PMID 37628606, 2023). "The BRCA2 c.67+3A > G variation (patient 20X0140), leading to exon 2 skipping, was found thanks to an abnormal junction of exons 1 to 3; however, an exon 1 to exon 4 junction was also evidenced in breast tumor tissue." (PMID 37046838, 2023). "Their study included 30 familial non-BRCA1/BRCA2 breast tumours." (PMID 37316882, 2023). "Moreover, the TNBC subtype is frequently seen in breast tumors arising in the BRCA1 mutation carriers (70%) and BRCA2 carriers (16–23%)." (PMID 35566456, 2022). "Similar results have been reported from another study cohort where the absence of BRCA2 locus-specific loss of heterozygosity was observed in 46% of breast tumors." (PMID 35052422, 2021). "Our analysis in BRCA2-associated breast tumours suggested that no genes were differentially variable." (PMID 34287743, 2021). "Interestingly, breast tumor samples with somatic damaging (nonsense, frameshift or missense) mutations in BRCA1 or BRCA2 genes showed a higher expression of Signature-3 score than tumors with BRCA1/2 wt genes." (PMID 34139015, 2021). "Comprehensive RECQL variant analysis was performed in 302 BRCA1 and BRCA2 negative patients with ER and/or PR positive breast tumors using denaturing high-performance liquid chromatography followed by DNA sequencing." (PMID 33342430, 2020). "In summary, we identified a single pathogenic RECQL variant in 302 BRCA1 and BRCA2 negative high-risk patients with ER positive and/or PR positive breast tumors." (PMID 33342430, 2020). "This is the first study that investigates the prevalence of pathogenic RECQL germline variants in 302 BRCA1 and BRCA2 negative high-risk patients with ER positive and/or PR positive breast tumors from Pakistan." (PMID 33342430, 2020). "In contrast to breast tumors associated with BRCA1, lack of caveolin-1 expression in breast tumors has been reported in patients with germline mutations in BRCA2, suggesting that the expression of caveolin-1 occurs only in tumors with mutations in BRCA1." (PMID 31244284, 2019). "BRCA2-associated breast tumors more often were PR positive compared to tumors of non-carriers (81.8% vs. 57.2%, p=0.025) (data not shown)." (PMID 31528241, 2019). "Ovarian and breast tumors with BRCA1 and BRCA2 mutations are sensitive to the PARP1 inhibitors." (PMID 31856867, 2019).
breast tumors (continued). "Here we present a systematic genomic analysis of breast tumors with BRCA1 and BRCA2 mutations." (PMID 31182087, 2019). "We next examined the correlation between BRE and CDC25A levels in BRCA2 mutant human breast tumors." (PMID 29416040, 2018). "Nevertheless, reports based on IHC or expression array analysis have shown that BRCA2 breast tumors are predominantly of the luminal B subtype, and are more likely than non-BRCA2 tumors to be ER positive and high grade, with reduced tubule formation and continuous pushing margins." (PMID 25857409, 2014). "The histopathologic characteristics of BRCA1 and BRCA2 breast tumors are well described." (PMID 24479546, 2014). "To develop more efficient approaches to screening we have compared the gene expression and genomic profiles of BRCA2-mutant breast tumors with those of breast tumors lacking BRCA1 or BRCA2 mutations." (PMID 23284877, 2012). "83% of BRCA1 breast tumours were ER−, whereas 76% of BRCA2 breast tumours were ER+." (PMID 22312502, 2011). "To date, two BRCA2 deficient tumours, two BRCA1 deficient tumours, and two BRCA1 deficient cell lines have also been subjected to medium-depth whole genome sequencing, as part of a wider study of primary breast tumours and cell lines." (PMID 21750719, 2011). "The study further dissects the role of methylation of candidate genes in sporadic breast tumorigenesis, its interaction with functional BRCA2 -26 SNP and the status of pro- and anti- apoptotic as well as DNA damage repair gene expression in breast tumor tissues." (PMID 21092294, 2010). "The observation of BRCA2 -26 G/A 5'UTR polymorphism concomitant with the presence of methylation in the promoter region was novel and emerged as a strong candidate for susceptibility to sporadic breast tumors." (PMID 21092294, 2010). "Clinical trials are currently underway to determine the efficacy of PARP inhibitors in treating BRCA deficient breast tumors, which may open new avenues for less toxic therapies that target particular DNA repair pathways in BRCA1 and BRCA2 mutation carriers." (PMID 21037853, 2010). "The detailed information on the locations of genomic alterations provided by the high-resolution CGH arrays used here allowed us to more clearly delineate the distinct genetic pathways undertaken by breast tumours displaying either BRCA1 or BRCA2 abnormalities." (PMID 19589159, 2009). "EMSY gene products are known to interact with and negatively regulate BRCA2 proteins and this may link the BRCA2 gene with sporadic breast tumour development." (PMID 19589159, 2009). "We then specifically addressed the question of whether the BRCA1 and BRCA2 genes are involved in sporadic breast tumour development." (PMID 19589159, 2009). "AI at the BRCA1 and BRCA2 loci are know to be relatively common in breast tumours." (PMID 16846527, 2006). "Interestingly, there is a nine-fold decreased expression of SFN in BRCA1- and BRCA2-related tumours compared to sporadic breast tumours." (PMID 16280053, 2005). "No sporadic breast tumours have been shown to harbour mutations in the coding sequence of BRCA1 or BRCA2." (PMID 12838319, 2003). "Interestingly, we noticed that breast tumors with mixed histology were mainly BRCA2-related." (PMID 39001430, 2024). "Importantly, the MiDAS sites identified in this study in cells lacking BRCA2 are enriched in chromosome rearrangements in BRCA2-mutated breast tumors." (PMID 36002001, 2022).